NRGN (neurogranin)
Diseases named in the same sentence as NRGN in open-access papers (continued):
Sharing a sentence is not in itself a finding about the gene and the disease.
hippocampal atrophy (3 papers, 2024 to 2025). "For instance, elevated CSF levels of neurogranin, a postsynaptic plasticity protein, have been associated with faster hippocampal atrophy and cognitive decline in some cohorts, whereas other studies have reported no such associations." (PMID 41442069, 2025). "The synaptic latent factor was composed of neurogranin, FABP3, and ferritin, and showed robust associations with hippocampal atrophy in both longitudinal and mediation models." (PMID 41442069, 2025). "When tested individually, neither ferritin nor neurogranin was significantly associated with hippocampal atrophy, whereas FABP3 showed a significant interaction effect." (PMID 41442069, 2025). "In this study, to further confirm our previous findings that reduced synaptic proteins in EVs are associated with the development of AD, we examined the relationship between concentrations of SNAP25, GAP43, neurogranin, and synaptotagmin 1 and degrees of hippocampal atrophy in patients with AD." (PMID 38528511, 2024).
mental disorder (3 papers, 2025). A disease that has its basis in the disruption of mental process. "Our data suggest that SNAP-25, NRXN3 and NRGN versus beta-amyloid and phosphorylated tau protein 181 (ptau) are regulated differentially across psychiatric disorders and that SNAP-25 has a moderate diagnostic potential for MDD and SCZ." (PMID 40840974, 2025). "We further performed interaction analyses with history of psychiatric disease for the SPM and CSF main analyses that were significant and found that history of psychiatric disease interacted with death of partner on p-tau and neurogranin (eTable 17)." (PMID 40163795, 2025).
asthma (2 papers, 2023 to 2025). "The results proved severe asthma to be associated with elevated levels of neurogranin, a biomarker indicative of synaptic degeneration, and alpha-synuclein linked to neurodegeneration." (PMID 39958092, 2025). "Elevated neurogranin levels, which have high specificity for AD, indicate that severe asthma might specifically increase the risk of AD-related dementia." (PMID 39958092, 2025). "Quantitative analyses revealed that neurogranin concentrations in patients with severe asthma were elevated by 147% compared to patients with mild asthma." (PMID 39958092, 2025). "For example, for NDI, a stronger negative association with neurogranin in those with asthma was found in the corticospinal tract, superior longitudinal fasciculus, anterior corona radiata and uncinate fasciculus in the left hemisphere." (PMID 37377978, 2023). "Additionally, neurogranin levels were found to be 123% higher in severe asthma patients than in non-asthmatic controls." (PMID 39958092, 2025). "Negative relationships between neurogranin concentrations and FA and NDI, and positive relationships between neurogranin and MD, RD, ODI, and FISO were present in the asthma group, but not among controls." (PMID 37377978, 2023).
delirium (2 papers, 2024 to 2025). A disorder characterized by confusion; inattentiveness; disorientation; illusions; hallucinations; agitation; and in some instances autonomic nervous system overactivity. "Neurogranin (Ng) has a role in synaptic plasticity and is considered a biomarker of synaptic dysfunction, a process hypothesised to be important in delirium." (PMID 41218946, 2025).
depression (2 papers, 2020 to 2022). "The functions of the proposed neuronal biomarker neurogranin, a calmodulin binding protein also involved in long term potentiation and depression, is detailed." (PMID 33027906, 2020).
Sepsis (2 papers, 2020 to 2025). Sepsis is defined as life-threatening organ dysfunction caused by a dysregulated host response to infection. "In Astrocyte 1, inflammation-associated genes (GFAP, FOS, C3, CD74) were significantly upregulated, while BBB-related genes (GRIA2, NRGN, TXNIP) were downregulated in sepsis." (PMID 41030458, 2025). "Gene entities shared between sepsis and severe sepsis response hubs are; TDRD9 – LIN7A, GPR84 – ENTPD7, PYCT1A and ZDHHC19, CD177 – DDAH2 and RGL4, SLC16A3 – DENND3 and MBD6, MYL9 – CMTM5, ITGB3, ITGA2B, NRGN, SELP and TREML1." (PMID 32318053, 2020).
cognitive (1 paper, 2020). "Many studies have suggested that increased baseline neurogranin levels are indicative of future cognitive deterioration in patients with MCI20,41,42, while a few studies have suggested that low baseline neurogranin levels are indicative of future cognitive deterioration." (PMID 32284537, 2020).
epileptic seizures (1 paper, 2023). "The results of this analysis showed that neurogranin levels in patients with epileptic seizures (confirmed with EEG data) were significantly higher than in PNES and non-epileptic controls." (PMID 36884195, 2023). "A recent report has shown that neurogranin changes in biofluids can distinguish epileptic seizures from psychogenic non-epileptic seizures (PNES) in adults." (PMID 36884195, 2023).
HIV-1 infection (1 paper, 2013). The type species of lentivirus and the etiologic agent of acquired immunodeficiency syndrome (AIDS). "HIV-1 infection itself down regulated NRGN expression as seen in LVL." (PMID 23721325, 2013).
Huntington disease (1 paper, 2018). Huntington disease (HD) is a rare neurodegenerative disorder of the central nervous system characterized by unwanted choreatic movements, behavioral and psychiatric disturbances and dementia. "We conclude that neither neurogranin nor TREM2 is a useful biofluid biomarker for disease processes in Huntington’s disease." (PMID 29523800, 2018). "Nonetheless we conclude that neither neurogranin nor TREM2 is likely to be of value as a CSF biomarker for disease processes in Huntington’s disease." (PMID 29523800, 2018).
Hypertension (1 paper, 2024). The presence of chronic increased pressure in the systemic arterial system. "Notably, neurogranin (NRGN) levels were significantly associated with hypertension and smoking, while casein alpha S1 (CSN1S1) levels varied with statin use." (PMID 39590217, 2024). "In contrast, hypertension, cardiovascular disease (CVD), and smoking were significantly associated with the abundance of neurogranin (NRGN)." (PMID 39590217, 2024). "Following adjustment for hypertension, CVD, or smoking, neurogranin was significantly different between the study groups." (PMID 39590217, 2024).
hypothyroidism (1 paper, 2014). Abnormally low levels of thyroid hormone. "In addition, the concentrations of Ca2+/calmodulin-independent protein kinase (CaMKII), neurogranin, SNAP-25 and calmodulin, in which changes were induced by hypothyroidism, have been found to return to basal levels following T4 replacement therapy." (PMID 24520241, 2014).
intracranial hemorrhage (1 paper, 2025). Bleeding within the SKULL, including hemorrhages in the brain and the three membranes of MENINGES. "While neurogranin concentrations did not significantly distinguish patients with intracranial hemorrhage from those without, this result reflects its sensitivity as a general indicator of brain injury rather than as a marker of lesion severity." (PMID 40981206, 2025).
Jacobsen syndrome (1 paper, 2021). A multiple congenital anomaly/intellectual disability contiguous gene syndrome caused by partial deletion of the long arm of chromosome 11. "Children with Jacobsen syndrome, which involves attention deficit hyperactivity disorder (ADHD), have a deletion in the NRGN gene." (PMID 33270377, 2021).
low grade glioma (1 paper, 2025). A grade I or grade II glioma arising from the central nervous system. "Interestingly, our DEG analysis also defined CCK and NRGN gene expression differences between C1 and C2 LGG subgroups as expected with the weaker expression in cerebellar low-grade gliomas (C2)." (PMID 40382536, 2025).
malaria (1 paper, 2024). Malaria is a serious and sometimes fatal disease caused by a parasite that commonly infects a certain type of mosquito which feeds on humans. "The increased levels of αSyn and NRGN in our Pk-infected patients suggest potential neurological implications, prompting further investigation into the underlying mechanisms of knowlesi malaria pathogenesis and their clinical significance over time." (PMID 39658124, 2024).
posterior cortical atrophy (1 paper, 2019). Posterior Cortical Atrophy (PCA) is a rare progressive neurodegenerative disorder with a typical onset between 50-65 years of age characterized by progressive impairment of higher visual processing skills and other posterior cortical functions without any evidence of ocular abnormalities. "However, in one previous study comparing neurogranin concentrations in typical and atypical AD, concentrations were higher in atypical AD (posterior cortical atrophy) than in controls, but higher still in amnestic AD." (PMID 31847891, 2019).
prion disease (1 paper, 2023). A transmissible disease that is caused by a protein that is able to induce abnormal folding of normal cellular proteins, leading to characteristic spongiform brain changes, which are associated with neuronal loss without an inflammatory response. "There are other markers of neuronal death that can complement the diagnosis of prion diseases, such as α-synuclein, S100b protein, glial fibrillary acidic protein (GFAP), neuron-specific enolase (NSE), and neurogranin, but their diagnostic efficacy is not fully established." (PMID 38133284, 2023).
synucleinopathies (1 paper, 2023). "Presynaptic accumulation of α-synuclein driving synaptic dysfunction instrinsic to synucleinopathies.Widespread reduction in synaptic density found with PET imaging.Some markers of synaptic plasticity (e.g. neurogranin and GAP-43) may correlate with ADNC." (PMID 37387459, 2023).
trauma (1 paper, 2025). "Unlike traditional biomarkers such as GFAP and NFL, which reflect glial and axonal injury, respectively, neurogranin highlights the synaptic dimension of brain trauma, which is highly relevant for cognitive outcomes and risk of later neurodegeneration." (PMID 40981206, 2025). "This systematic review addresses the following research question: Is neurogranin a reliable biomarker for diagnosis, prognosis, and mechanistic understanding of mild traumatic brain injury across different biofluids and timepoints?" (PMID 40981206, 2025).
neurodegenerative disease (18 papers, 2015 to 2025). A disorder of the central nervous system characterized by gradual and progressive loss of neural tissue and neurologic function. "Taken together, these findings reinforce neurogranin’s broader role as a marker of synaptic pathology and highlight its potential to link acute synaptic injury after mTBI with long-term risk of neurodegenerative disease." (PMID 40981206, 2025). "In this review, the diagnostic value of cerebrospinal fluid neurogranin in most common neurodegenerative diseases is examined." (PMID 39769345, 2024). "Associated with neurodegenerative diseases increase in neurogranin concentration in CSF and blood has therefore been viewed as a specific marker of disruption of synaptic integrity and plasticity." (PMID 36884195, 2023). "Neurogranin and α-synuclein are other two neuronal proteins explored as biomarkers of neurodegenerative diseases." (PMID 36884195, 2023). "In line with previous studies, we have shown that neurogranin differentiated well between AD and other neurodegenerative diseases." (PMID 26698298, 2015). "Literature data indicate that cerebrospinal fluid neurogranin may be useful as a biomarker for more accurate diagnosis and prognosis of neurodegenerative diseases." (PMID 39769345, 2024). "Therefore, the topic of the usefulness of neurogranin in the diagnosis of neurodegenerative diseases and the possibility of its determination in CSF, as discussed in this article, raises both medical and legal issues." (PMID 39769345, 2024). "In this regard, recent studies found that CSF levels of synaptosomal-associated protein 25 (SNAP-25) and neurogranin (Ng), both enriched in synapses, might distinguish CJD from other neurodegenerative diseases accurately and have prognostic potential." (PMID 37684653, 2023). "Instead, biomarkers reflecting synaptic dysfunction and/or damage (such as neurogranin, synaptosomal-associated protein 25, SNAP-25, and β-synuclein) have been investigated mostly investigated in cerebrospinal fluid (CSF) samples of patients with neurodegenerative diseases, but are unexplored in MS." (PMID 39708160, 2024). "Neurogranin may also have a potential in differentiation of neurodegenerative diseases." (PMID 39769345, 2024). "Indeed, establishing a RI and decisional cut off of neurogranin could help to appropriately evaluate the clinical usefulness of such biomarker in patients with neurodegenerative diseases and promote its introduction in clinical practice." (PMID 34943576, 2021). "Thus, we could not state that neurogranin is a specific biomarker of AD and further studies must be performed to assess whether neurogranin could be used as a biomarker for differential diagnosis among neurodegenerative diseases." (PMID 34943576, 2021). "The aim of this study was to examine the synaptic biomarker neurogranin in cerebrospinal fluid (CSF) in different stages of HIV infection and in relation to what is known about CSF neurogranin in other neurodegenerative diseases." (PMID 30649659, 2019). "Deranged synaptic and immune function have been reported in HD, and concentrations of the synaptic protein neurogranin and the microglial protein TREM2 are increased in other neurodegenerative diseases." (PMID 29523800, 2018). "Interestingly, CSF neurogranin was not elevated in our cohort of patients with other neurodegenerative diseases." (PMID 26698298, 2015). "Unlike the other synaptic proteins, for example, neurogranin, SNAP-25, and Syt1, the CSF 14-3-3 protein levels were also increased in other neurodegenerative diseases, which indicates that they could be general markers of neurodegeneration." (PMID 38246483, 2024).
tumor (5 papers, 2021 to 2024). "MAML2, a tumor suppressor gene with high methylation modification but loss of protein expression, and NRGN, a tumor gene with low methylation modification but upregulated protein expression, can be used as biological indicators to judge the malignant transformation of SNIP-SCC." (PMID 38427106, 2024). "Subsequently, compared with non-neoplasia nasal epithelial tissues, the expression of HLA-G and NRGN was upregulated in grade I, II, III and IV tissues, while the expression of MAML2 was lost." (PMID 38427106, 2024). "Shared decreased protein-coding genes across all tumor types included FOXP2, GABRA1/2/4/5, NRGN, SST, and SYNPR." (PMID 36865335, 2023).
neurological disease (3 papers, 2019 to 2024). "We measured CSF SNAP-25, β-synuclein, and neurogranin in 48 untreated PwMS and 50 controls with other neurological diseases (ONDs) and tested their associations with neuropsychological and MRI data." (PMID 39708160, 2024). "Its abundance in spinal cord tissue was also associated with a decrease in the intensity of neurogranin and neurofilament medium, both of which are biomarkers for neurological disease." (PMID 36951542, 2023).
brain diseases (2 papers, 2020 to 2022). "However, in terms of the differentiation of AD from other brain disorders, synaptic proteins (e.g., neurogranin and VILIP-1) are useful, whereas axonal injury markers (e.g., NFL) are not." (PMID 32284537, 2020). "The well-characterized CaMBP neurogranin (Ng, RCE, p17, BICKS) is not only a useful biomarker for AD, but also for PD, as well as Creutzfeldt–Jakob disease and other brain diseases." (PMID 36421678, 2022).
cancer (1 paper, 2024). A tumor composed of atypical neoplastic, often pleomorphic cells that invade other tissues. "Our study found a significantly downregulated methylation loci CG26069044 in the NRGN gene in SNIP-SCC, which may be a new finding of NRGN expression dysregulation in cancer." (PMID 38427106, 2024).
NRGN also shares sentences with these, for which no sentence is quoted: Anxiety (4 papers); Cerebral ischemia (3); multiple system atrophy (3); psychosis (3); bipolar disorder (2); cardiovascular disease (2); Creutzfeldt Jacob disease (2); memory impairment (2); progressive supranuclear palsy (2); vascular dementia (2); angiosarcoma (1); autism (1); brain tumor (1); breast carcinoma (1); cerebrovascular diseases (1); cognitive disorder (1); cortical atrophy (1); corticobasal syndrome (1); Encephalopathy (1); epilepsy (1); familial Alzheimer disease (1); hip fracture (1); infarction (1); inverted papilloma (1); ischemic stroke (1); Neurodegeneration (1); neurodevelopmental disorder (1); peripheral neuropathy (1); sickle cell disease (1); subarachnoid hemorrhage (1).
A further 3 diseases each share a sentence with NRGN in 1 paper.